AHR (aryl hydrocarbon receptor)
Diseases named in the same sentence as AHR in open-access papers (continued):
Sharing a sentence is not in itself a finding about the gene and the disease.
tumor (continued). "A recent genome wide analysis of AhR and AhRR binding found a significant overlap in sequences binding both proteins, suggesting that AhRR most likely functions as a tumor suppressor by opposing AhR-driven gene expression." (PMID 33763068, 2021). "Tryptophan catabolites can activate AhR to enhance tumor malignancy and inhibit anti-tumor immunity." (PMID 34458309, 2021). "Rutaecarpine is a natural compound with potential tumor therapeutic effects which can possibly bind to AhR." (PMID 34955744, 2021). "Conversely, other studies have aimed to promote activation of AhR through the use of agonists when the transcription factor acts as a tumor suppressor." (PMID 33451095, 2021). "KYN, the first metabolite of KP, can function as an endogenous ligand to activate the aryl hydrocarbon receptor (AhR) in an autocrine/paracrine fashion, and emerging evidence points toward the tumour-promoting role of KYN-mediated activation of the AhR." (PMID 34680327, 2021). "Further, we validated the contribution of AhR in Breg differentiation using AhR-/- mice at day-9 post tumor implant, AhR-/- mice exhibited significantly lowered Breg frequency compared to WT control mice." (PMID 34867973, 2021). "L-Kyn mediated AhR activation promotes tumor growth with elevated levels of inflammatory cytokines (IL-6, IL-8, and IL-1β) and a decreased frequency of infiltrating cytotoxic CD8+ T cells in TME." (PMID 34867973, 2021). "Transgenic mice with a constitutively active AhR spontaneously develop tumors and the repressor of the AhR (AHRR) functions as a tumor suppressor in multiple human tumors." (PMID 32443455, 2020). "Studies in this laboratory also showed that the AhR exhibited tumor suppressor-like activity in glioblastoma cells." (PMID 32932962, 2020). "An IDO1/AhR inhibitor reversed the tumor dormancy response and resulted in reduced spheroid growth after exposure to IFNγ in vitro." (PMID 33379189, 2020). "Surprisingly, all analyzed tumor samples showed higher expression of AhR than normal thyroid at the mRNA level." (PMID 31936153, 2020). "Enhanced kynurenine levels within the tumor microenvironment stimulates AHR activation within T-cells resulting in elevated PD1 expression, which in combination with tumor cell intrinsic PDL1 expression introduce immune checkpoints leading to immune tolerance." (PMID 33348604, 2020). "The aryl hydrocarbon receptor (AHR), a potential tumor suppressor and NLRP3 regulator, was higher in hen (2.4x increase, p = 0.002) and human tumors (1.8x increase, p = 0.038), suggesting a role in OvCa." (PMID 31923221, 2020). "The activation of the AhR signal pathway by the cellular responses against environmental toxins and carcinogens elicits hepatotoxicity and tumor propagation in liver." (PMID 32183141, 2020). "As a confirmation, IHC staining for AhR showed stained nuclei, index of AhR nuclear migration and transcriptional activation, especially in the regions of tumor invasion." (PMID 31936153, 2020). "AIP, a co-chaperone protein that acts as a tumor suppressor in pituitary cells, is critical for AHR stabilization and function." (PMID 33281746, 2020). "In summary, our findings revealed that AhR plays a critical role in maintaining the stem-like properties of cells overexpressing UCHL3, confirming that UCHL3 promotes tumor stem-like properties through stabilizing AhR." (PMID 32546741, 2020). "Such tumor-suppressive effects of these miRNAs were exerted through the modulation of ERα and Aryl Hydrocarbon Receptor (AhR) signaling pathways." (PMID 32759784, 2020). "Eighty one percent of patients with high AhR signaling responded well to anti PD-1 antibody pembrolizumab, while 75% patients with progressive disease exhibited low AhR in tumor tissues." (PMID 33076303, 2020). "Based on these findings, we sought to explore the effects of using selective AHR inhibitors in controlling tumor growth." (PMID 32782249, 2020).
tumor (continued). "The direct effect of the AHR on the gene transcription gives it powerful influence on the carcinogenesis and tumor progression." (PMID 32907554, 2020). "Further mechanistic studies are warranted to understand the pro- or anti-tumor effects of AHR agonists and antagonists and the contextual role of the AHR in these processes." (PMID 33203443, 2020). "And DIM as a selective modulator of AHR, has been demonstrated it has inhibitory effects on tumor proliferation, migration and invasion." (PMID 32546278, 2020). "Aryl hydrocarbon receptor (AHR) has been reported to promote tumor metastasis and epithelial-mesenchymal transition (EMT) is a vital process of conferring cancer cells capabilities of migration and invasion." (PMID 32546278, 2020). "As such, the regulation of TGF-β, across cells of the tumour microenvironment is important to the regulation of immune suppression, including following AhR activation." (PMID 33375613, 2020). "Kyn has been considered to be a potent agonist of AhR, which can regulate the differentiation and activity of immune cells and thus suppress the immune response against tumors, leading to tumor immune tolerance." (PMID 33542896, 2020). "This was in contrast to a previous report, and there are other examples of apparent differences in the functional roles of the AhR in other tumor types." (PMID 32932962, 2020). "Under such conditions, AHR activation by kynurenine promotes intrinsic AHR-dependent tumor cell survival combined with reshaping of the immunological milieu to invoke an immune tolerant environment within solid tumors." (PMID 33348604, 2020). "It is worth noting that these flavonoids are based on their own structural characteristics, chemical nature, and function as an AhR agonist to play an anti-tumor effects." (PMID 33542691, 2020). "Our results thus reveal AhR as a potential therapeutic target for BCa tumours presenting a genetic alteration triggering an AhR pathway activation." (PMID 32988402, 2020). "A cut-off point for relative expression of AHR and cytochrome 450 enzymes (CYP1A1, CYP1A2, and CYP1B1; markers of AHR activation) was determined to compare with the grade, stage, and tumor progression." (PMID 32907554, 2020). "We have also shown that the natural AhR antagonist resveratrol, used in combination with BRAFi, prevents the emergence of persister-resistant cells and thus delays tumor growth in vivo." (PMID 32708687, 2020). "The increase in KYNs is suggested to play an important role in the pathophysiology of tumor immune tolerance via activation of AhR signaling." (PMID 32957545, 2020). "Collectively, these reports suggest entity- and stage-dependent functions of AHR in carcinogenesis and tumor progression." (PMID 33214553, 2020). "On the other hand, KYNA is an endogenous agonist of AhR which is involved in several processes including cell proliferation, apoptosis, adipose differentiation, tumour suppression and immune cell differentiation." (PMID 31659416, 2020). "kynurenine, a tryptophan-derived ligand that activates and bridges AhR to chronic inflammation and breast carcinogenesis." (PMID 32722276, 2020). "As such, suppressed pineal melatonin will modulate the AhR influence on the tumour microenvironment, including over the circadian rhythm." (PMID 33375613, 2020). "Evidences show that I3C can exert its anti-tumor properties through regulating cell growth, cell cycle and division, apoptosis and metastasis mainly through aryl hydrocarbon receptor (AHR)." (PMID 32546278, 2020). "Factors associated with the induction of ‘exhaustion’ in CD8+ T cells and NK cells within the tumour microenvironment, include the AhR, TGF-β, CD73 (ecto-5-Nucleotidase), adenosine A2Ar activation, PD-1, and the COX2/PGE2/EP4 pathway." (PMID 33375613, 2020). "This cell line allowed us to assess the effect of AHR expression in both the mouse host and the tumor cells to the effects of TCDD." (PMID 32398692, 2020).
tumor (continued). "UALCAN database showed AHR expression levels significantly correlated with tumor grade, lymph node metastasis and clinical stages." (PMID 32546278, 2020). "Increased AhR expression and nuclear translocation was detected in invasive and malignant tumor cell lines." (PMID 32957545, 2020). "AHR is positively correlated to overall survival in ER positive tumors supporting a tumor suppressor function." (PMID 32132611, 2020). "This same study also determined that AhR plays dual tumour suppressor roles; as a regulator of intestine anti-inflammation and β-catenin degradation." (PMID 32456012, 2020). "On this basis, we generated a docking model of emodin and AhR to provide a potential explanation for the anti-tumor effects of this drug as an AhR agonist." (PMID 33542691, 2020). "The mRNA expression of CYP1A1 (p = 0.002), CCL20 (p = 0.047), p19 (p = 0.029), CCL19 (p = 0.013), IL-36γ (p = 0.0076), and IL-17 (p = 0.0035) was significantly decreased in tumor from AhR-(fl/fl) Krt5-(Cre) mice compared with wild type mice." (PMID 33178182, 2020). "AhR is overexpressed in various types of tumors and tumor cell lines, suggesting that AhR is activated constitutively in tumors and facilitates their growth." (PMID 32325928, 2020). "TDO-derived Kyn suppresses antitumor immune responses and promotes tumor-cell survival and motility through the AHR in an autocrine/paracrine fashion." (PMID 32050636, 2020). "Altogether, our in vitro data thus demonstrated the role of the AhR/GPR30 cross-talk in favoring tumor progression, at least in a triple-negative breast context." (PMID 32670863, 2020). "In this study, it was demonstrated that TDO-derived kyn suppresses antitumor immune responses and stimulates tumour-cell survival and migration through the AHR in an autocrine/paracrine fashion." (PMID 32776284, 2020). "All these data confirmed that the lack of detectable sequence amplification is restricted to the 5’ upstream region of AHR exon 10 and present exclusively in tumor tissue." (PMID 33281746, 2020). "In turn the tumor suppressor AHRR (aryl hydrocarbon receptor repressor) inhibits AHR and reduces inflammation and cancer progression." (PMID 31923221, 2020). "Increased AHR expression is so consistent in some tumor types that it has been proposed as a prognostic marker." (PMID 33396563, 2020). "The mechanism by which UCHL3 promotes tumor stem-like properties through AhR requires further investigation." (PMID 32546741, 2020). "The role of the AhR and its ligands have been extensively investigated and there is evidence that AhR expression exhibits both tumor-promoting and tumor-suppressive activities and this is dependent on the tumor type." (PMID 32731514, 2020). "As expected, sequence analysis showed a degenerated letter codes in tumor DNA as compared to DNA from blood of the same patients and healthy pituitary tissue, suggesting a putative upstream deletion in the AHR exon 10 only in tumor tissue." (PMID 33281746, 2020). "Activation of the AhR/COX2/PGE2 pathway in tumours leads to PGE2 release and EP2 and EP4 activation in different cells, in turn increasing TGF-β release, and TGF-β-induced adenosine, from these cells and thereby contributing to cytolytic cell ‘exhaustion’." (PMID 33375613, 2020). "Recently, AhR has been shown to support BC growth by controlling reactive oxygen species (ROS) levels and the tumor-promoting features of macrophages." (PMID 32054109, 2020). "Importantly, the expression of IDO1 and TDO is controlled by the AhR and, when increased, causes depletion of local tryptophan pools in the microenvironment, suppression of antigen-specific T cell responses, and promotion of T regulatory (Treg) cell differentiation during tumor development." (PMID 32824193, 2020). "TDO regulates tumor activity and the immune response via the Try-Kyn-aryl hydrocarbon receptor (Ahr) pathway, and similar research has also been reported in breast cancer." (PMID 32532962, 2020).
tumor (continued). "Blockage of AhR prevents the activation of immune-tolerant dendritic cells and Treg in tumor microenvironment." (PMID 32899152, 2020). "We finally showed that BCa cells presenting those genetic alterations affecting the AhR pathway were dependent on AhR for their viability, suggesting AhR as a potential therapeutic target for these tumours." (PMID 32988402, 2020). "Does tumour-derived kynurenine activation of the AhR on tumour microenvironment cells differentially regulate acetyl-CoA and the melatonergic pathway in these cells, including an increase in the NAS/melatonin ratio?" (PMID 33375613, 2020). "Since inflammation is one of the factors that favors and supports tumor transformation through several factors, among which AhR, it is reasonable to include AhR among the targets of a combined anti-inflammatory/antitumoral therapy." (PMID 32722276, 2020). "Kynurenine is an endogenous ligand of AhR, a cytosolic ligand-dependent transcription factor that is reported to promote tumorigenesis and tumor aggressiveness." (PMID 32824193, 2020). "Our results show that Imaging-AMARETTO recapitulates known key drivers of tumor-associated microglia and macrophage mechanisms (STAT3, AHR, and CCR2) and neurodevelopmental and stemness mechanisms (OLIG2)." (PMID 32383980, 2020). "IDO expressed by TAMs and tumor cells metabolizes tryptophan to kynurenine, and kynurenine inhibits T-cell immunity while stimulating Mφ aryl hydrocarbon receptor (AHR) expression." (PMID 32707672, 2020). "The indole-3-carbinol metabolite, diindoilmetano (DIM), has also demonstrated antitumor activity mediated by AhR acting on tumor stem cells." (PMID 32443455, 2020). "Regarding to the AhR, it have a role in TCDD toxicity, but also is involved in tumorigenesis and is found at elevated levels in aggressive tumors and tumor cell lines, however with the variant the binding site for this transcription factor is destroyed." (PMID 30642281, 2019). "Further research showed that IFN-β mobilized the IDO1/Kyn/AhR/p27-dependent pathway to mediate tumor cells dormancy." (PMID 31297335, 2019). "In 37 patients treated with anti-PD-1 antibody pembrolizumab, 13/16 (81.3%) patients who achieve partial response or stable disease express high levels of AhR, whereas 12/16 (75%) patients with progression disease exhibit low levels of AhR in tumor tissues." (PMID 30850589, 2019). "For instance, blocking IDO-kynurenine-AhR metabolic circuitry abolishes immunologic latency mediated by IFN-γ in tumor-repopulating cells (TRCs)." (PMID 31430951, 2019). "In recent years, the aryl hydrocarbon receptor’s role in carcinogenesis has often been discussed, elucidating its pro-oncogenic and anti-tumorigenic roles depending on the tumor type." (PMID 31212758, 2019). "In contrast, a chronic activation of cutaneous AHR signaling critically contributes to premature aging and the development of neoplasms by affecting metabolism, extracellular matrix remodeling, inflammation, pigmentation, DNA repair, and apoptosis." (PMID 31795255, 2019). "The proposed mechanism of TCDD involves stimulation of the aryl hydrocarbon receptor (AhR), which upregulates cellular signaling, DNA binding and transcriptional activation leading to tumor-promoting activities." (PMID 31131286, 2019). "Staining for AhR was obtained for 302 primary BC tissues and observed in the nucleus and/or cytoplasm of tumor cells." (PMID 30813617, 2019). "AhR is expressed by many cell types, including immune cells, which are important in anti-tumor response." (PMID 31417567, 2019). "In prostate tumor cells, AhR shows aberrant expression and its deletion or inhibition results in the inhibition of tumorgenesis and tumor growth." (PMID 30766532, 2019). "Instead, in another study, benzo[a]pyrene was shown to cause cancer in an AhR-dependent manner and similarly, the endogenous AhR modulator kynurenine promotes tumor formation through the AhR." (PMID 32009975, 2019).
tumor (continued). "Expression of the aryl hydrocarbon receptor (AhR) has been described in various tumor entities from different organs." (PMID 31212758, 2019). "High AhR immunoreactivity was present in a large proportion of BC tissues (91.1% of tumor cells in the whole cohort, and similar percentages in the LN-negative or -positive sub-groups)." (PMID 30813617, 2019). "We were able to show that the immunohistochemical evaluation of cytoplasmic AhR correlated with histology, grading (except in low-grade serous cancer), tumor size, and FIGO." (PMID 31212758, 2019). "In microenvironments with ample oxygen and nutrient availability, tumor cells can employ the TDO2-Kyn-AHR axis to suppress the immune system." (PMID 31866995, 2019). "Increased AhR expression and activity is believed to build a pro-inflammatory tumor environment, leading to tumor progression." (PMID 31212758, 2019). "Taken together, these results suggest that AHR activation promotes tumor induction of PAH-induced skin carcinogenesis." (PMID 31552251, 2019). "Univariate analysis of clinical specimens revealed that a longer overall survival is achieved in the group with lower expression of tryptophan 2,3-dioxygenase 2 (TDO2) and AHR in cells surrounding the tumor." (PMID 31552251, 2019). "Then kynurenine activates AHR in tumor-repopulating cells, which enters them into dormancy, the condition resistant to immune-therapies." (PMID 31552251, 2019). "In a recent study, the expression of AhR was observed in the cytoplasm and nucleus of tumor cells and in their microenvironment, with high levels being correlated with the high expression of several genes related to inflammation and invasion." (PMID 30813617, 2019). "Blockade of IDO/AhR metabolic circuitry not only nullifies IFN-γ-mediated latency but also promotes amplified tumor cell growth arrest by IFN-γ-dependent killing of TRCs in vitro and in vivo." (PMID 31430951, 2019). "AHR signaling was recently shown to enhance PD-L1 expression on tumor cells and decreased response to immune checkpoint blockade in lung cancer." (PMID 31795255, 2019). "Concerning the correlation between AhR expression and BC patient survival, our data clearly indicated that this correlation depends on the LN status of the tumor." (PMID 30813617, 2019). "Another similar pathway that is active in tumor cells as well as in Th cells is aryl hydrocarbon receptor (AhR)." (PMID 30766532, 2019). "The authors concluded that the continuing activation of AhR via endogenous ligands such as kynurenine represent a critical event in tumor promotion resulting in increased survival of cancer cells." (PMID 31035533, 2019). "CYP1B1 and other CYP enzymes are regulated by the aryl hydrocarbon receptor (AHR), which is a ligand-activated transcription factor involved in the tumor-promoting properties of different environmental contaminants like PAHs." (PMID 31370872, 2019). "The substrate of the KMO enzyme, KYN, was shown to promote tumor formation and the generation of regulatory T cells via AHR and adenylate- and guanylate-cyclase pathway activation." (PMID 31781097, 2019). "This different expression status of AHR plays a critical role in pro- or anti-tumor activity according to the cell state." (PMID 31552251, 2019). "Activation of AHR by tumor-produced Kyn is believed to elicit a gene expression program that not only results in the paracrine suppression of immune cells but also facilitates cancer cell proliferation and migration in a cell-autonomous manner." (PMID 31416966, 2019). "The mechanisms of TCDD-mediated toxicity and AhR-dependent tumor promoting activity have been investigated in numerous studies with a focus on TCDD’s action as a potent hepatic tumor promoter." (PMID 31035533, 2019). "AHR mRNA expression level was assessed in the cohort of 439 tumor specimens and was compared to normal breast tissue samples." (PMID 29320557, 2018).